SLC19A3 (solute carrier family 19 member 3)
Description:
Mediates high affinity thiamine uptake, probably via a proton anti-port mechanism. Has no folate transport activity. Mediates H(+)-dependent pyridoxine transport.
Synonyms: ThTr-2; ThTr2; hTHTR2; BBGD; THMD2
Tractability: Small molecule: a structure with a bound ligand is known. Antibody: its Gene Ontology location is reachable by antibodies, with high confidence; UniProt predicts a signal peptide or a membrane-spanning region; the Human Protein Atlas places it where antibodies can reach. PROTAC: its protein half-life has been measured.
Gene: Protein-coding gene on chromosome 2 (227,683,763 to 227,718,088, reverse strand). Ensembl gene ENSG00000135917.
Subcellular location: Membrane
Subcellular location (Human Protein Atlas): Nucleoplasm; Plasma membrane; Cytosol
Pathways (Reactome):
Metabolism: Vitamin B1 (thiamin) metabolism
Gene Ontology:
Molecular function: protein binding; thiamine transmembrane transporter activity; vitamin transmembrane transporter activity
Biological process: pyridoxine transport; thiamine transport; thiamine transmembrane transport; thiamine-containing compound metabolic process; thiamine diphosphate biosynthetic process; vitamin transport
Cellular component: membrane; plasma membrane
Genetic constraint (gnomAD): Loss-of-function variants: 29 observed, 40.83 expected, observed/expected ratio (o/e) 0.71, 90% interval 0.53 to 0.97. The upper end of that interval is the gene's LOEUF score, 0.97, which puts it in group 4 of 6, group 1 being the genes least tolerant of losing a copy. Missense variants: 588 observed, 623.46 expected, observed/expected ratio (o/e) 0.94, 90% interval 0.88 to 1.01. Synonymous variants: 212 observed, 240.6 expected, observed/expected ratio (o/e) 0.88, 90% interval 0.79 to 0.99.
Gene-disease validity (ClinGen):
ClinGen rates the evidence that SLC19A3 causes each of these diseases.
Leigh syndrome (autosomal recessive): Definitive. A progressive neurological disease defined by specific neuropathological features associating brainstem and basal ganglia lesions.
Homologues: Orthologues: chimpanzee SLC19A3 (99% identical), macaque SLC19A3 (95% identical), dog SLC19A3 (82% identical), rabbit SLC19A3 (82% identical), guinea pig SLC19A3 (78% identical), pig SLC19A3 (76% identical), mouse Slc19a3 (68% identical), rat Slc19a3 (63% identical), tropical clawed frog cptp (51% identical), tropical clawed frog slc19a3 (51% identical), tropical clawed frog slc19a3.2 (45% identical), zebrafish slc19a3a (44% identical), and 6 more. Paralogues in human: SLC19A2 (49% identical), SLC19A1 (38% identical).
Diseases named in the same sentence as SLC19A3 in open-access papers:
SLC19A3 is named in the same sentence as 78 diseases in open-access papers, as found by Europe PMC text mining. Sharing a sentence is not in itself a finding about the gene and the disease. The quoted sentences say what the papers report.
Thiamine deficiency (11 papers, 2013 to 2025). Thiamine deficiency is a condition that occurs due to not enough thiamine (vitamin B1). "Mutations in thiamine transporter genes, SLC19A2 and SLC19A3, have been observed in cases of thiamine deficiency due to decreased absorption of thiamine that leads to neurological dysfunction." (PMID 32564308, 2020). "The inhibition of SLC19A3 can lead to organism-wide and tissue-specific thiamine deficiencies." (PMID 39358356, 2024).
Leigh syndrome (9 papers, 2014 to 2024). "The clinical characteristics distinguishing treatable thiamine transporter-2 deficiency (ThTR2) due to SLC19A3 genetic defects from the other devastating causes of Leigh syndrome are sparse." (PMID 24957181, 2014). "The MRI pattern of brain injury involving the dorsal striatum and medial thalamic nuclei in patients with SLC19A3 defect may be useful to distinguish this disorder from other causes of Leigh syndrome." (PMID 24957181, 2014). "MRS may show lactate peaks during the acute phase in SLC19A3 defects and in other causes of Leigh syndrome." (PMID 24957181, 2014). "We detected pathogenic mutations in the SLC19A3 gene in 1 of 11 patients with Leigh syndrome." (PMID 24957181, 2014). "In two families with classical Leigh-syndrome we identified a defect in the thiamine transporter SLC19A3, where despite a decrease in mitochondrial oxygen consumption, complex activities seemed normal in muscle, and skin tissue." (PMID 30369941, 2018). "SLC19A3 gene has been associated with neuropathies including Thiamine responsive encephalopathy type 2 (OMIM #607483), severe psychomotor retardation and progressive atrophy, Wernicke’s-like encephalopathy (OMIM #606152), and Leigh syndrome (OMIM #256000)." (PMID 34614013, 2021). "Furthermore, mutations in thiamine metabolism genes SLC19A3, SLC25A19 and TPK15, 7, 12, 13 have been reported to result in Leigh syndrome, a progressive neurodegenerative disorder of early childhood." (PMID 28706281, 2017).
biotin-responsive basal ganglia disease (7 papers, 2010 to 2023). Any thiamine-responsive dysfunction syndrome in which the cause of the disease is a variation in the SLC19A3 gene, characterized by subacute encephalopathy with confusion, seizures, and movement disorder, often following a history of febrile illness. "Biotin-responsive basal ganglia disease (DYT-SLC19A3) is a recessive disorder caused by mutations of the SLC19A3 gene, coding for a transporter related to the reduced-folate and thiamin." (PMID 35207493, 2022). "We had two patients investigated in our cohort manifesting symptoms of biotin-responsive basal ganglia disease (BBGD), P37, and P38, which presented homozygous mutations c.74dupT (p.Ser26Leufs*19) and c.980-14A>G, respectively, in SLC19A3." (PMID 37628588, 2023). "Biotin-responsive basal ganglia disease (BBGD) with SLC19A3 mutation was first reported in 1998, and over 30 mutations have been reported." (PMID 36175418, 2022). "There is a phenotypic spectrum of diseases in people associated with abnormalities in different regions of the SLC19A3 gene, including biotin-responsive basal ganglia disease (BBGD), Wernicke's-like encephalopathy (WLE), and an encephalopathy described in 4 related Japanese boys." (PMID 23469184, 2013). "Mutations in SLC19A3 (encoding hTHTR2) cause a neurometabolic autosomal recessive disorder known as thiamine metabolism dysfunction syndrome type 2 or biotin-responsive basal ganglia disease (BBGD) or biotin-thiamine responsive basal ganglia disease (BTBGD; OMIM: 607483)." (PMID 37153911, 2023). "Evaluation of this region for candidate genes uncovered SLC19A3 as a likely candidate, based on the phenotypic similarities between people affected with biotin-responsive basal ganglia disease (BBGD) and dogs with AHE." (PMID 23469184, 2013). "Genetic defects in ThTr1 (SLC19A2) and ThTr2 (SLC19A3) result in thiamine-responsive megaloblastic anemia (TRMA) and biotin-responsive basal ganglia disease (BBGD), respectively." (PMID 27379239, 2016).
breast carcinoma (6 papers, 2011 to 2022). "In this study, we further confirmed that frequent down-regulation of SLC19A3 expression in breast cancer is associated with hypermethylation of its promoter CpG region." (PMID 21789241, 2011). "Although this finding suggests plasma level of methylated SLC19A3 may serve as an early diagnostic marker for breast cancer, further validations in larger DCIS cohorts are necessary." (PMID 21789241, 2011). "We confirmed this positive correlation for SLC19A3 by analyzing breast cancer patient data in the TCGA database using UCSC Xena and by data mining in bc-GenExMiner v.4.2." (PMID 34414945, 2021). "Although SLC19A3 expression was repressed, transport assays demonstrated an increase uptake of thiamine in all breast cancer cell lines tested compared to hMECs." (PMID 24280319, 2013). "An elevation of SLC19A3 methylation was detected in the plasma of early- and advanced-stage breast cancer patients as well as gastric cancer." (PMID 24280319, 2013). "Upregulation of TPK-1, SLC19A2, SLC25A19 and downregulation of SLC19A3 was also verified in several breast cancer cell lines compared to human mammary epithelial cells (hMECs)." (PMID 24280319, 2013). "Our results showed that methylated SLC19A3 DNA in plasma was significantly higher in both gastric and breast cancer patients than those of controls (All P-values<0.0001; Mann-Whitney U test)." (PMID 21789241, 2011). "At a cutoff point of 0.41 (relative plasma level of methylated SLC19A3 DNA), the sensitivity was 87% and the specificity was 85% in discriminating breast cancer from control subjects." (PMID 21789241, 2011). "Our results showed that plasma level of methylated SLC19A3 DNA was significantly elevated in breast cancer patients compared with those of controls." (PMID 21789241, 2011). "Plasma level of methylated SLC19A3 DNA was assessed on a group of 165 plasma samples including 60 breast cancer patients, 45 gastric cancer patients and 60 healthy controls." (PMID 21789241, 2011). "To explore the possibility of using this methylated SLC19A3 DNA as a marker for breast cancer detection, we developed a robust and simple methylation-sensitive restriction enzyme-based quantitative assay to measure methylated SLC19A3 DNA in plasma." (PMID 21789241, 2011). "SLC19A3 down-regulation frequently occurred in cancers including breast cancer." (PMID 21789241, 2011). "In particular, SLC19A3 (solute carrier family 19, member 3 or THTR-2, thiamine transporter-2) which has been found to be down-regulated in gastric and breast cancer, could be a potential candidate for this diagnostic purpose." (PMID 21789241, 2011). "To examine the expression level of SLC19A3 gene, we performed qRT-PCR on 15 pairs of primary breast cancer tumor tissues and their adjacent non-tumor breast tissues from 15 Chinese female breast cancer patients." (PMID 21789241, 2011).
Encephalopathy (6 papers, 2013 to 2025). Encephalopathy is a term that means brain disease, damage, or malfunction. "In people, mutations in the SLC19A3 gene (encoding a thiamine transporter protein) are associated with encephalopathies that have some clinical and neuropathologic similarities to AHE." (PMID 23469184, 2013). "While the BBGD phenotype is thought to be secondary to a loss-of-function mutation, the Japanese boy encephalopathy may be due to a toxic gain-of-function secondary to the SLC19A3 mutation." (PMID 23469184, 2013). "This SLC19A3–related condition is an autosomal recessive disorder with childhood-onset that presents as a subacute encephalopathy and progresses to severe cogwheel rigidity, dystonia, quadriparesis, and eventually death if left untreated (OMIM 606152)." (PMID 33081289, 2020).
Dystonia (4 papers, 2014 to 2025). An abnormally increased muscular tone that causes fixed abnormal postures. "In two siblings with early-onset encephalopathy dystonia and epilepsy, whole-exome sequencing revealed a novel single heterozygous SLC19A3 mutation (c.337T>C)." (PMID 26863430, 2016). "Although SLC19A3 deficiency is considered to be a treatable entity, the literature review showed that sixty percent of previously reported patients with either BTBGD or a Leigh phenotype had poor outcomes, including early death, tetraparesis, dystonia or cognitive impairment." (PMID 24957181, 2014).
gastric cancer (4 papers, 2011 to 2022). A primary or metastatic malignant neoplasm involving the stomach. "When exogenously re-expressing SLC19A3 in gastric cancer cells, a marked decrease in growth rate was found." (PMID 24280319, 2013). "Previously, we have examined the methylation status of SLC19A3 (solute carrier family 19, member 3) promoter and found that SLC19A3 was epigenetically down-regulated in gastric cancer." (PMID 21789241, 2011). "Plasma SLC19A3 methylated DNA level was effective in differentiating both breast and gastric cancer from healthy subjects." (PMID 21789241, 2011). "The objective was to apply such SLC19A3 MSRED-qPCR to investigate the possibility of using such marker as a novel diagnostic marker for breast and gastric cancer." (PMID 21789241, 2011). "SLC19A3 is down-regulated via promoter methylation in gastric cancer." (PMID 25749033, 2015). "To find out the role of hub genes in the overall survival of gastric cancer we performed a multivariate Cox regression analysis, among 21 hub genes, the eight genes (KCNJ3, CPVL, ONECUT2, SLC19A3, DDC, PRSS21, F12, and GRTP1) were designated as independent indicators of poor prognosis." (PMID 35754804, 2022). "Previously, we showed that SLC19A3 but not SLC19A2 was frequently down-regulated through promoter hypermethylation in gastric cancer." (PMID 21789241, 2011). "In our previous study of gastric cancer, we showed that SLC19A3 but not SLC19A2 was down-regulated through promoter hypermethylation." (PMID 21789241, 2011). "Importantly, elevation of plasma methylated SLC19A3 DNA level has been detected in not only advanced stages but also pre-cancerous DCIS and early stages of tumor suggesting a potential marker for early breast and gastric cancer detection." (PMID 21789241, 2011).
Thiamine-responsive encephalopathy (4 papers, 2021 to 2022). "Thiamine and biotin treatment in biotin- or thiamine-responsive encephalopathy (mutations in SLC19A3), folinic acid in cerebral folate deficiency (mutations in FOLR1), and creatine in cerebral creatine deficiency (mutations in SLC6A8) are other examples." (PMID 33726816, 2021). "Mutations in the SLC19A3 gene encoding for thiamine transporter-2 (THTR2) are responsible for biotin-responsive basal ganglial disease and thiamine-responsive encephalopathy." (PMID 34091762, 2021).
Cognitive impairment (3 papers, 2014 to 2021). Abnormal cognition is characterized by deficits in thinking, reasoning, or remembering. "Transcripts predictive of cognitive performance under high stress included genes that are associated with a high occurrence of Alzheimer's and cognitive impairments (e.g., Ncl, Eno1, Scn9a, Slc19a3, Ncstn, Fos, Eif4h, Copa, etc.)." (PMID 28912681, 2017). "Targeting genes implicated in both isolated and syndromic forms of cognitive impairment has allowed us to select two variants of interest in GHR and SLC19A3 genes." (PMID 34614013, 2021).
diabetes (3 papers, 2021 to 2022). "Our present results, together with previous data on cells of the inner blood-retinal barrier, and the evidence that two SNPs located in the SLC19A3 gene are strongly associated with absent or minimal DR and DN, account for a primary involvement of THTR2 in diabetes microvascular complications." (PMID 33916491, 2021).
Obesity (3 papers, 2019 to 2025). Accumulation of substantial excess body fat. "Genes functionally non-reported in adipose tissue showed a link with a GWAS obesity trait (SLC19A3 and UPK3B genes) and a GWAS blood lipids trait (LVRN, CD300LG, and HAS1 genes)." (PMID 30816281, 2019).
Biotin deficiency (2 papers, 2024). "Early biotin deficiency inhibits SLC19A3 expression, but as the deficiency worsens, it instead stimulates SLC19A3 expression and increases biotin transport." (PMID 40217438, 2024). "Biotin deficiency reduced SLC19A3 gene expression, suggesting that managing biotin intake could be a method for regulating the expression of SLC19A3." (PMID 39125325, 2024).
colon cancer (2 papers, 2024 to 2025). "Reduced expression of THTR2 (SLC19A3) was found in malignant breast, gastric, and colon cancer as compared to physiologic expression in normal tissue." (PMID 39797340, 2025).
type 1 diabetes (2 papers, 2021). "It was also demonstrated that two single-gene polymorphisms (SNP) located in the SLC19A3 gene encoding for THTR2 are associated with resistance to the development of DR and DN, in subjects with long-term type 1 diabetes." (PMID 33916491, 2021). "This confirms our previous findings on retinal cells of the inner blood-retinal barrier, and the relevance of genetic mutations of the SLC19A3 gene encoding for THTR2 in the resistance to the development of DR and DN in subjects with long-term type 1 diabetes." (PMID 33916491, 2021).
Wernicke encephalopathy (2 papers, 2022 to 2024). An acute neurological disorder characterized by the triad of ophthalmoplegia, ataxia, and disturbances of mental activity or consciousness. "Additional SLC19A3 variations were described in Leigh and Leigh-like syndromes, in BTRBGD disease and in Wernicke’s encephalopathy." (PMID 36093993, 2022).
arthrogryposis (1 paper, 2021). A rare, non-progressive congenital disorder characterized by multiple joint contractures which are present at birth. "Specifically, in infants 5/8 (63%) had a genetic disease including Noonan-like syndrome (P1), Laron-syndrome (P3), mitochondriopathy (SLC19A3 mutation) (P5), Turner-syndrome (P8), and arthrogryposis (P14)." (PMID 33083944, 2021).
Atrophy (1 paper, 2010). Any weakening or degeneration, especially through lack of use. "In the present study, we demonstrated that a homozygous mutation (E320Q) in SLC19A3 is associated with epileptic spasms in early infancy, severe psychomotor retardation and characteristic MRI findings, including progressive brain atrophy and bilateral thalami and basal ganglia lesions." (PMID 21176162, 2010).
breast tumors (1 paper, 2011). "SLC19A3 expression was significantly down-regulated in 80% (12/15) of breast tumors (P<0.005)." (PMID 21789241, 2011).
cognitive decline (1 paper, 2021). "We hypothesize that GHR and SLC19A3 genes might act either as genetic modifiers that exacerbate the severity of cognitive decline induced by the primary disease-causing mutation in the MAN2B1 gene or as additional disease loci co-segregating with AM." (PMID 34614013, 2021).
congenital heart disease (1 paper, 2021). A heart disease that is present at birth. "Three children aged between 2 and 12 years had the following main diagnoses: mitochondriopathy (SLC19A3 mutation) (P 4), ependymoma (P11) and complex congenital heart diseases (P 18)." (PMID 33083944, 2021).
diabetic retinopathy (1 paper, 2021). "Two single nucleotide polymorphisms located in the SLC19A3 gene encoding for THTR2 may be associated with protection from diabetic retinopathy and nephropathy in type 1 diabetic subjects with long disease duration." (PMID 34091762, 2021).
episodic ataxia (1 paper, 2023). "P37 developed neonatal epileptic encephalopathy with homozygous c.980-14A>G in SLC19A3 and P38 displayed episodic ataxia with homozygous c.74dupT (p.Ser26Leufs*19)." (PMID 37628588, 2023).
gout (1 paper, 2025). A condition characterized by painful swelling of the joints, which is caused by deposition of urate crystals. "We characterized the SLC19A3 gene variants using bioinformatics and analyzed DNA samples from controls, T2DM, and gout patients to explore associations with physical/laboratory parameters." (PMID 40243602, 2025). "We studied how variations in the SLC19A3 gene, encoding THTR2, a thiamine transporter, may influence type 2 diabetes (T2DM) and gout (arthritis urica, AU)." (PMID 40243602, 2025).
lactic acidosis (1 paper, 2025). Metabolic acidosis characterized by the accumulation of lactate in the body. "Biotin and/or thiamine were used more frequently in neonatal lactic acidosis or acute Leigh syndrome, to treat the possibility of deficiency of the SLC19A3 thiamine transporter, biotinidase or pyruvate dehydrogenase complex." (PMID 39529390, 2025).
myopia (1 paper, 2025). "To determine the expression levels of SLC19A2 and SLC19A3 in the choroidal tissues of myopic guinea pigs at different myopia induction times, we performed immunofluorescence staining of the choroidal tissues of myopic guinea pigs." (PMID 40351473, 2025).
rigid spine muscular dystrophy 1 (1 paper, 2016). An inherited muscular dystrophy caused by mutations in the SEPN1 gene. "Indeed, both detected mutations, p.G196R in SLC19A3 and p.G239R in SEPN1, had been previously reported in patients with either HHRH or rigid spine muscular dystrophy-1 (RSD-1), respectively." (PMID 26789268, 2016).